PLSCR3 (phospholipid scramblase 3)
Description:
Catalyzes calcium-induced ATP-independent rapid bidirectional and non-specific movement of the phospholipids (lipid scrambling or lipid flip-flop) between the inner and outer membrane of the mitochondria. Plays an important role in mitochondrial respiratory function, morphology, and apoptotic response. Mediates the translocation of cardiolipin from the mitochondrial inner membrane to outer membrane enhancing t-Bid induced cytochrome c release and apoptosis. Enhances TNFSF10-induced apoptosis by regulating the distribution of cardiolipin in the mitochondrial membrane resulting in increased release of apoptogenic factors and consequent amplification of the activity of caspases. Regulates cardiolipin de novo biosynthesis and its resynthesis.
Tractability: Antibody: its Gene Ontology location is reachable by antibodies, with high confidence; UniProt predicts a signal peptide or a membrane-spanning region. PROTAC: ubiquitination databases record sites on it; its protein half-life has been measured.
Gene: Protein-coding gene on chromosome 17 (7,389,727 to 7,397,054, reverse strand). Ensembl gene ENSG00000187838.
Subcellular location: Mitochondrion membrane; Mitochondrion inner membrane; Nucleus
Subcellular location (Human Protein Atlas): Mitochondria
Gene Ontology:
Molecular function: calcium ion binding; calcium-dependent protein binding; lead ion binding; magnesium ion binding; mercury ion binding; phospholipid scramblase activity; protein binding
Biological process: apoptotic process; mitochondrial membrane organization; regulation of apoptotic process; regulation of release of cytochrome c from mitochondria; plasma membrane phospholipid scrambling; cellular response to lipopolysaccharide
Cellular component: cytosol; mitochondrial membrane; mitochondrion; plasma membrane; mitochondrial inner membrane; nucleus
Genetic constraint (gnomAD): Loss-of-function variants: 16 observed, 29.16 expected, observed/expected ratio (o/e) 0.55, 90% interval 0.37 to 0.83. The upper end of that interval is the gene's LOEUF score, 0.83, which puts it in group 3 of 6, group 1 being the genes least tolerant of losing a copy. Missense variants: 353 observed, 355.26 expected, observed/expected ratio (o/e) 0.99, 90% interval 0.91 to 1.09. Synonymous variants: 164 observed, 143.02 expected, observed/expected ratio (o/e) 1.15, 90% interval 1.01 to 1.3.
Homologues: Orthologues: chimpanzee PLSCR3 (99% identical), macaque PLSCR3 (99% identical), pig PLSCR3 (95% identical), rabbit PLSCR3 (94% identical), mouse Plscr3 (93% identical), dog PLSCR3 (92% identical), guinea pig PLSCR3 (92% identical), rat Plscr3 (92% identical), zebrafish plscr3b (51% identical), zebrafish si:ch211-71m22.1 (43% identical), zebrafish si:ch211-71m22.5 (41% identical), zebrafish plscr3a (39% identical), and 13 more. Paralogues in human: PLSCR1 (50% identical), PLSCR2 (41% identical), PLSCR5 (40% identical), PLSCR4 (39% identical).
Diseases named in the same sentence as PLSCR3 in open-access papers:
PLSCR3 is named in the same sentence as 13 diseases in open-access papers, as found by Europe PMC text mining. Sharing a sentence is not in itself a finding about the gene and the disease. The quoted sentences say what the papers report.
dyslipidemia (2 papers, 2007 to 2022). "One such candidate, that encoding phospholipid scramblase 3 (PLSCR3), was recently identified, as genetic deletion of it led to lipid accumulation in abdominal fat pads and changes characteristic of metabolic syndrome." (PMID 17355638, 2007). "Mice deficient in PLSCR3 were found to accumulate lipid in abdominal fat pads and were characterized with insulin resistance, dyslipidemia, and glucose intolerance, classic tell-tale markers for metabolic syndrome." (PMID 17355638, 2007). "Since Plscr3 knockout mice showed a higher accumulation of abdominal fat as well as insulin resistance, glucose intolerance, and dyslipidemia, we aimed to investigate the role of PLSCR4 in other models of lipid accumulation." (PMID 36077184, 2022).
Glucose intolerance (2 papers, 2016 to 2022). Glucose intolerance (GI) can be defined as dysglycemia that comprises both prediabetes and diabetes. "PLSCR3 gene knockout (Plscr3−/−) mice accumulated abdominal fat and displayed insulin resistance and glucose intolerance." (PMID 27571067, 2016).
Obesity (2 papers, 2007 to 2024). Accumulation of substantial excess body fat. "In humans, Plscr3 and Sar1b are linked to obesity and lipid metabolic disease, respectively, Kif21a is linked to ocular disease, and Nlgn2 is linked to schizophrenia (MGI)." (PMID 38968323, 2024). "Metabolic profiling of mice deficient in phospholipid scramblase 3 reveals a possible molecular link between obesity and inflammation." (PMID 17355638, 2007). "The development of murine models deficient in PLSCR proteins provides a means to elucidate the biochemistry underlying Plscr3-mediated obesity." (PMID 17355638, 2007). "Not only do LPC molecules present a potential link between obesity, inflammation, and atherogenesis, the acyl composition of LPC suggests that Plscr3-deficient mice may have modified desaturase enzyme activities and eicosanoid metabolism." (PMID 17355638, 2007).
atherosclerosis (1 paper, 2012). A disease characterized by the build-up of fatty material and calcium deposition in the arterial wall resulting in partial or complete occlusion of the arterial lumen. "In particular, NR5A1 is known to be a nuclear receptor that regulates the transcription of many genes involved in atherogenesis and PLSCR3 has been proved to be related to atherosclerosis development by animal studies." (PMID 22244445, 2012).
cardiac arrest (1 paper, 2011). Cessation of breathing and/or cardiac function. "Cardiac arrest increased levels of phosphorlyated PLSCR3; however, inhibition of δPKC translocation failed to affect the OGD-induced increase in PLSCR3 in synaptosomal mitochondria suggesting the post-ischemic phosphorylation of PLSCR3 is not mediated by δPKC." (PMID 21789211, 2011).
Cerebral ischemia (1 paper, 2011). Restriction of arterial blood supply to the brain associated with insufficient oxygenation to support the metabolic requirements of the tissue. "It is possible that following cerebral ischemia, PLSCR3, modified by δPKC, may result in impaired cardiolipin – cytochrome c interaction leading to cytochrome c release." (PMID 21789211, 2011). "We observed that PLSCR3 phosphorylation was indeed increased following in vivo cerebral ischemia." (PMID 21789211, 2011). "Thus, δPKC activation/translocation was dissociated from phosphorylation of PLSCR3 and fails to mechanistically explain the increase in cytochrome c release following cerebral ischemia." (PMID 21789211, 2011).
infection (1 paper, 2022). The state of being infected such as from the introduction of a foreign agent such as serum, vaccine, antigenic substance or organism. "The few proteins for which a fold-change >2 or <−2 was observed 48 h after infection are involved in apoptosis (SCARF1, PLSCR3), ubiquitination (UBE2E3, OTULIN), or the response to type I IFN (OAS2)." (PMID 35337059, 2022).
myopathy (1 paper, 2022). A disease of the muscle in which the muscle fibers do not function properly. "Moreover, expression of PLSCR3, encoding phospholipid scramblase 3, which is associated with mitochondria-mediated apoptosis, was not significantly changed in myopathy skin fibroblasts compared to control skin fibroblasts." (PMID 35216315, 2022).
PLSCR3 also shares sentences with these, for which no sentence is quoted: colorectal cancer (1 paper); diabetic retinopathy (1); Insulin resistance (1); schizophrenia (1); tumor (1).